FLNA (filamin A)
Diseases named in the same sentence as FLNA in open-access papers (continued):
Sharing a sentence is not in itself a finding about the gene and the disease.
connective tissue disease (1 paper, 2018). "These two new cases expand the list of live-born FLNA mutation-positive males with connective tissue disease from eight to ten, contributing to a better knowledge of the genetic and phenotypic spectrum of FLNA-related disease." (PMID 30089473, 2018). "Here, we report on two male cases with connective tissue disease and brain abnormalities who carry novel FLNA mutations." (PMID 30089473, 2018).
heart disease (1 paper, 2018). "Our results therefore suggest that ADAR2 does not primarily act in the nervous system, but rather the cardiovascular system, where editing in sites such as FLNA plays a key role in regulating vascular constriction, thereby protecting against cardiac remodeling and resulting heart disease." (PMID 30087110, 2018).
intestinal diseases (1 paper, 2024). "Relevant proteins such as CALU, FLNA, MSN and HMGA2, which are related to intestinal diseases, were all upregulated in the IBD duodenal organoids." (PMID 38203746, 2024).
lymph node (1 paper, 2019). "In this study, we confirmed that a Filamin A (FLNA)-derived hsa_circ_0092012 known as circFLNA, was upregulated in LSCC, and the higher expression of circFLNA was correlated with LSCC lymph node metastasis." (PMID 31384171, 2019).
myopathies (1 paper, 2017). "Filamins are comprised of three homologous proteins—Filamin A, B, C. Human mutations in FLNB have been associated primarily with skeletal anomalies, whereas FLNC mutations cause myopathies." (PMID 29240780, 2017).
neurodevelopmental disorder (1 paper, 2025). A behavioral and cognitive disorder with onset during the developmental period that involves impaired or aberrant development of intellectual, motor, or social functions. "Mutations in the FLNA gene, which encodes the FLNA protein, are linked to various neurodevelopmental disorders." (PMID 40365811, 2025). "Disruption of FLNA function can lead to abnormal neuronal positioning, resulting in cortical malformations and associated neurodevelopmental disorders, highlighting the indispensable role of FLNA in brain development." (PMID 40365811, 2025). "Disruptions in FLNA function can lead to abnormal neuronal positioning, impaired synaptic formation and altered connectivity, resulting in a spectrum of neurodevelopmental disorders, including PVNH, FCMs and ASD." (PMID 40365811, 2025).
FLNA also shares sentences with these, for which no sentence is quoted: Periventricular heterotopia (17 papers); otopalatodigital syndrome (5); adrenocortical carcinomas (3); Hearing impairment (3); hypospadias (3); Micropenis (3); neuronal migration disorders (3); Obesity (3); pulmonary neuroendocrine tumors (3); Aortic dissection (2); cervical cancer (2); intestinal obstruction (2); laminopathies (2); Loeys-Dietz syndrome (2); osteochondrodysplasia (2); otopalatodigital syndrome type 2 (2); parathyroid carcinoma (2); phyllodes tumor (2); thrombosis (2); West syndrome (2); Acute hepatitis (1); acute monocytic leukemia (1); Adams-Oliver syndrome 5 (1); adrenal cancer (1); and Muscular Disorder (1); ankylosing spondylitis (1); Apathy (1); arrhythmogenic right ventricular cardiomyopathy (1); arterial diseases (1); ascending aortic aneurysm (1).
A further 82 diseases each share a sentence with FLNA in 1 paper.